BRAF (B-Raf proto-oncogene, serine/threonine kinase)
Diseases named in the same sentence as BRAF in open-access papers (continued):
Sharing a sentence is not in itself a finding about the gene and the disease.
melanoma (continued). "The clinical application of BRAF and MEK inhibitors has changed the prospect of melanoma treatment, especially the combination therapy with both agents." (PMID 34054126, 2021). "Beginning in 2011, novel therapies, including immunotherapy with immune checkpoint inhibitors CTLA-4 or PD-1, as well as targeted therapy with BRAF and MEK inhibitors, have become a key breakthrough in the clinical landscape of melanoma treatment." (PMID 35004285, 2021). "Treatment with BRAF and MEK inhibitors rapidly and significantly reduces the addiction of melanoma cells to glycolytic processes." (PMID 34073463, 2021). "We have now demonstrated that, in melanoma, EZH2 represses miR-129-5p, dependent on constitutive active BRAF signaling." (PMID 34063443, 2021). "Our study includes data from BRAF-mutant G361 and Hs294T as well as NRAS-mutant SK-MEL-2 melanoma cells." (PMID 33937086, 2021). "Despite the tremendous clinical therapeutic advantage induced by ICIs and BRAF/MEK inhibitors, further improvements in the therapy of patients with advanced melanoma are needed." (PMID 33804800, 2021). "ICIs inhibit negative regulatory mechanisms and boost the antitumor activity of the host’s immune system, while targeted therapy directed against aberrant signaling molecules (BRAF and MEK) will block the uncontrolled proliferation and expansion of melanomas." (PMID 34769156, 2021). "We demonstrate here that RGS and BRAF/MEK inhibitors induce CD40 expression on murine melanoma cell lines and responsive patient melanoma cells in PDX models." (PMID 34092233, 2021). "Belvarafenib is a selective RAF dimer (type II) inhibitor with clinical efficacy in BRAF and NRAS-mutant melanomas." (PMID 34804979, 2021). "In A375 BRAF-mutant melanoma cells, DETD-35 showed superior activity to DET in sensitizing PLX4028 (PLX) to attenuate PLX-resistant A375-R melanoma growth." (PMID 33810045, 2021). "Melanoma or non-small cancer cells, among other cancer cells, acquire drug resistance by upregulating EGFR after BRAF exposure." (PMID 34360915, 2021). "RAF monomer (BRAF (V600)) inhibitors (such as vemurafenib, dabrafenib, and encorafenib) are clinically approved for the treatment of BRAFV600 mutant melanoma." (PMID 34685488, 2021). "The first trial to investigate the safety and efficacy of the combined BRAF and MEK inhibition in patients with BRAFV600-mutant melanoma patients with MBMs was COMBI-MB." (PMID 34859235, 2021). "Usp9x knockdown in melanoma increased SOX2 ubiquitination, leading to its depletion, and enhanced apoptotic effects of BRAF inhibitor and MEK inhibitors." (PMID 33613844, 2021). "Thereafter, selective BRAF inhibitors replaced the previously used chemotherapies in treating BRAFV600E and BRAFV600K mutant melanoma in clinics, which significantly improved patient survival." (PMID 34621046, 2021). "Based on promising preclinical data, combined BRAF, MEK and CDK4/6 inhibition has recently entered clinical trials for the treatment of BRAFV600 melanoma." (PMID 34025662, 2021). "Upon Usp9x KD, colony growth in 3D culture was blocked in both BRAF (A375) and NRAS (WM1366)-mutant melanoma cells." (PMID 33613844, 2021). "Combined MEK and CDK4/6 inhibition is a promising therapeutic option in mutant BRAF and NRAS melanoma." (PMID 34804979, 2021). "The introduction of BRAF/MEK inhibitors and immune checkpoint inhibitors offers new hope for patients with stage IV melanoma." (PMID 34771649, 2021). "The combination of dabrafenib (BRAF inhibitor) and trametinib (MEK inhibitor) is approved to treat Braf V600E mutant melanoma patients." (PMID 33841154, 2021).
melanoma (continued). "As a consequence of the BRAF inhibitor treatment, activating ligands MICA, ULBP3 and PVR are decreased on melanoma cells, thus contributing to diminished NK cell activation and further support of immune escape." (PMID 34572949, 2021). "From the third melanoma dataset, from TCGA SKCM117, there was enough BRAF-mutant samples available for analysis, mostly from metastatic disease." (PMID 33712615, 2021). "Current research shows that BRAF, NRAS, and C-Kit genes are closely related to the pathogenesis of melanoma." (PMID 34805163, 2021). "In the same study, it was shown that combination of a BRAF inhibitor and a MEK inhibitor led to an adaptive increase in ALDHhigh subpopulations in a subset of melanoma cell lines." (PMID 35048028, 2021). "In this regards, single-site biopsy of PLA1A could be considered as a diagnostic marker of BRAF-mutant metastasis in melanoma cancer, since it is sufficiently sensitive and precise in distinguishing melanoma patients with BRAF-mutated and NRAS-mutated advanced melanoma." (PMID 33723350, 2021). "However, mutations in BRAF have been found in up to 80% of benign nevi that rarely further progress to melanoma, thus indicating that BRAF alteration alone is not sufficient for melanoma development." (PMID 34830947, 2021). "Oncogenic mutations in RAS genes (KRAS, NRAS, and HRAS) or RAF genes (RAF-1, BRAF, and A-RAF) occur in many cancer types, including the melanoma cells." (PMID 34822435, 2021). "Multiple clinical trials evaluated CDK4/6 inhibitors as single agent regimen or in combination with BRAF ± MEK inhibitors as first or subsequent line of therapy in patients with advanced solid tumors, including melanoma." (PMID 34071228, 2021). "Presence of unusual variants of BRAF mutations seen in 3 of our cases might be more in favor of metastatic NSCLC than melanoma, given the vanishing rarity of these variant mutations in dedifferentiated melanoma and, instead, the predominance of the classical V600E mutation in melanoma." (PMID 33506327, 2021). "In line with this, E3 ligase alterations were shown to affect the BRAF and mitogen-activated protein kinase (MAPK) pathways, melanoma migration, and differentiation." (PMID 33800394, 2021). "LT correlates with improved OS in melanoma patients with BM in the era of ICI and anti-BRAF therapy." (PMID 34503304, 2021). "Here, we aim to determine the role of LRIG1 in melanoma tumorigenesis, RTK signaling, and BRAF inhibitor resistance." (PMID 33947959, 2021). "Pan-RAF inhibitors, such as belvarafenib, which can target BRAFV600E, the BRAF wild-type, and CRAF have shown anti-tumor efficacy in NRAS mutant melanomas in a phase 1 dose escalation study with an ORR of 44%." (PMID 34831002, 2021). "BRAF inhibitor-resistant melanoma cells are sensitive to recombinant LRIG1, which should be further explored as a potential therapy to combat BRAF inhibitor-resistance." (PMID 33947959, 2021). "Genetic alterations in BRAF and NRAS, as well as a handful of tumor suppressors such as NF1, CDKN2A, ARID2 and PTEN, have been shown to contribute to melanoma pathogenesis." (PMID 33958721, 2021). "Vemurafenib and MEKi treatment induced SOX2 in a time-dependent manner in both BRAF- and NRAS-mutant melanoma." (PMID 33613844, 2021). "Trial studies are ongoing to investigate the effect of bcl-2 family pan inhibitors in combination with BRAF and MEK inhibitors in melanoma patients (ClinicalTrials.gov Identifier: NCT01989585)." (PMID 33803452, 2021). "Another study showed that after short-term BRAF inhibition, PTEN-null melanoma cells acquire a CAF-like phenotype, especially regarding their ability to generate a fibronectin-derived protective niche, that allows therapeutic escape." (PMID 34067929, 2021). "In addition, metastasis could be the only clinical feature of melanoma with an unknown BRAF status." (PMID 34207125, 2021). "In melanoma patients, the survival benefit from LRIG1 depends on EGFR levels and is lost in BRAF and RAS mutant subtypes." (PMID 33947959, 2021).
melanoma (continued). "Preclinical evidence suggests the antitumor synergistic efficacy of CDK4/6 inhibitors, with BRAF/MEK inhibitors and MEK inhibitors, in BRAF and NRAS mutant melanomas, respectively." (PMID 34831002, 2021). "Of these, one had a BRAF mutant melanoma (ETH-E), two had NRAS mutant melanomas (SK-G & ETH-J), and three were BRAF/NRAS/NF1 wild-type (MI-F, SK-H, ETH-F)." (PMID 33664264, 2021). "We generated trametinib and dabrafenib resistant melanoma (TDR) cell lines to the MEK and BRAF inhibitors, respectively." (PMID 34831014, 2021). "In patients with V600 BRAF mutated melanoma, optimal treatment sequencing is unknown given the lack of randomized, outcome data from studies systematically sequencing the order of anti-PD-1 and anti-BRAF targeted treatment." (PMID 33435389, 2021). "To date, BRAF plus MEK inhibitors have shown a remarkable survival and response rate in advanced and unresectable melanoma patients, compared with single-agent BRAF inhibition." (PMID 33402199, 2021). "Overall, these data indicate that the BRAF pathway inhibitor resistant cells have elevated IGF1R at the mRNA level and melanoma patients with elevated IGF1R and INSR have a worse survival compared to patients with low levels of IGF1R." (PMID 34831014, 2021). "As an example, vemurafenib does not produce high efficacy in BRAF V600 mutated colorectal cancer with an overall response rate of 5%, whereas vemurafenib is highly effective in BRAF V600 mutated non-small cell lung cancer and melanoma with an overall response rate around 45%." (PMID 34199382, 2021). "Due to the fact that melanoma cells resistant to vemurafenib maintained sensitivity to DCA, this approach suggests a possible combination therapy to overcome BRAF inhibitors resistance in patients with melanoma." (PMID 33730175, 2021). "Therefore, we propose that combining dabrafenib, trametinib, and an IGF1R/IR inhibitor in patients with BRAF-mutant melanoma who have relapsed or dabrafenib and trametinib therapy regimen could be an effective strategy and warrants further investigation in the clinic." (PMID 34831014, 2021). "BRAF inhibition is known to permit infiltration of T cells and together with MEK inhibition increases antigen presentation in melanoma models." (PMID 33255891, 2020). "Overall, these results showed that cell lines with SCS interaction sets for BRAF/MAPK inhibitors were significantly enriched with tissues originating from the skin (59.2%, all melanoma) and large intestine (18.4%, all colorectal cancer)." (PMID 33203961, 2020). "The combination of a BRAF inhibitor and a MEK inhibitor has been shown to be more effective than a single agent in treating melanoma." (PMID 33194591, 2020). "The BRAF inhibitors vemurafenib, dabrafenib and encorafenib are used in the treatment of patients with BRAFV600-mutant advanced melanoma." (PMID 32645969, 2020). "One study has reported that resistance to anti-BRAF, anti-MEK, and combination treatments was mediated by formation of the eIF4F translation initiation complex in melanoma, colon, and thyroid cancer cell lines." (PMID 32637352, 2020). "As oncogenic signaling pathways activated in melanoma converge on the protein synthesis machinery, melanoma may be more sensitive to perturbation than normal cells and the effect was not restricted to cells containing mutant active BRAF V600E but also occurred with cell lines lacking the mutation." (PMID 32637352, 2020). "Atualmente, 3 inibidores BRAF (dabrafenibe, vemurafenibe e encorafenibe) e 3 inibidores MEK (trametinibe, cobimetinibe e binimetinibe) estão aprovados para o tratamento do melanoma." (PMID 33295473, 2020). "We selected melanoma MM334X, a PDX that originally demonstrated a significant response to BRAF and MEK therapy in vivo." (PMID 31857724, 2020).
melanoma (continued). "Importantly, TM synergized with Vemurafenib, the standard of care drug used in patients with late stage disease harboring the BRAFV600E mutation and could be additively or synergistically combined with Cobimetinib in both BRAFV600E and BRAF WT melanoma cell lines in inducing anti-cancer effects." (PMID 32085796, 2020). "In preclinical BRAF-mutant melanoma, co-administration of PLX3397 (CSF1R inhibitor) together with PLX4720 (mutant BRAF inhibitor) effectively sensitizes a PD-1-resistant tumor model to anti-PD-1/PD-L1 therapies." (PMID 32849557, 2020). "When compared to untreated control cells, Western blot data showed that FKB treatment (0–10 μg/mL, 24 h) dose-dependently suppressed the expressions of BRAF and its downstream p-ERK1/2 proteins in BRAF-expressing melanoma A375 cells." (PMID 33053749, 2020). "The initial skin lesion was a BRAF-mutant melanoma with Spitzoid features and termed as AST, while the giant lung metastasis was NRAS-mutant melanoma." (PMID 33100226, 2020). "Such involvement of DRP1 in tumorigenic potential and metabolic reprograming downstream of KRAS/BRAF is supported by some previous studies in separate models of PDAC and melanoma." (PMID 33738242, 2020). "First, we performed Sulforhodamine B (SRB) toxicity assay with two mutant BRAF inhibitors vemurafenib and dabrafenib, and a MEK inhibitor selumetinib alone and in combination in PF49 and A375 melanoma cells." (PMID 32591993, 2020). "As another example of paracrine signaling between CAFs and tumor cells, the hepatocyte growth factor (HGF) is secreted by the stroma upon treatment with BRAF or EGFR inhibitors, conferring resistance to melanoma and NSCLC cells, respectively." (PMID 33291749, 2020). "BRAF and MEK inhibitors combined with A2AR blockade show significant benefit in controlling melanoma tumor growth and metastasis in mice." (PMID 32351498, 2020). "The patients with BRAF K601E (case DM072) and BRAF G466R + NRAS Q61H mutant melanoma (case DM071) progressed after 4 and 7 months, respectively, each with stable disease as best response." (PMID 31839677, 2020). "Overall, PDXCs recapitulate the resistance to BRAF and MEK inhibitor therapy observed in the patient, and PDXCs from treatment-naive BRAF-mutant melanoma patients showed a marked response to BRAF and MEK inhibitor therapy." (PMID 31857724, 2020). "As such, MCL-1 inhibitors strongly sensitized BRAF and NRAS driven melanoma cell lines to inhibition of the RAF-MEK-ERK pathway, more so than inhibitors of BCL-2/BCL-XL, and more so than in ERK pathway-driven colorectal cancer cell lines." (PMID 31988312, 2020). "Pembrolizumab, an anti-PD-1 antibody, improved progression-free survival compared to BRAF inhibitors and PD-L1 inhibitors in clinical trial of stage III melanomas." (PMID 32626712, 2020). "The most striking clinical responses to inhibitors of BRAF, MEK, and EGFR have been observed in melanoma and lung cancers where RAS pathway activation is intrinsic." (PMID 32245042, 2020). "Increasingly, gene fusions involving various kinases, including ALK, ROS1, BRAF, RAF1, NTRK1, and NTRK3 have been identified within melanomas, and these fusion-positive melanomas often display spitzoid morphology." (PMID 32483240, 2020). "For example, EGFR/KRAS/ALK in non-small cell lung carcinoma, or BRAF, NRAS in melanoma, in agreement with the ESMO guidelines." (PMID 31787752, 2020). "Even if a combination of BRAF and MEK inhibitors shows an unparalleled response rate in melanoma, a large proportion of patients eventually relapse." (PMID 32466585, 2020). "To mimic the clinical scenario of patient relapse from targeted therapy, we also used BRAF- and MEK-inhibitor treated melanoma cell lines, resistant up to doses of 5 μM and 200 μM, respectively." (PMID 32513939, 2020). "RAF kinase fusions, such as of BRAF or RAF1 (also known as CRAF), have been reported in various tumor types, including prostate cancer, GC, melanoma, and papillary thyroid cancer." (PMID 32411236, 2020).
melanoma (continued). "Our in vitro data suggested that the combination of an MCL1 inhibitor and ABT-199 was effective against all melanomas, but higher concentrations were necessary for the BRAF-MUT compared to the BRAF-WT." (PMID 32764384, 2020). "The introduction of immunotherapy and novel therapeutics (BRAF and MEK inhibitors) has improved the outcome of melanoma patients." (PMID 33308268, 2020). "Overall, HI-511 mediates growth and apoptosis in both vemurafenib-sensitive and -resistant melanoma cells by targeting AURKB and BRAF V600E." (PMID 32863956, 2020). "In response to ERK and MEK inhibition, AXL/MITF-mediated drug resistance is observed among mutant BRAF and NRAS melanoma cell lines." (PMID 32245042, 2020). "Rearrangements in several genes, including BRAF, RET, ROS1, ALK, NTRK1, and NTRK3, have been characterized in subsets of melanoma." (PMID 32123303, 2020). "All 37 were wild type for BRAF, NRAS, and NF1 genomic alterations (“triple wild-type”), representing 2.0% of triple wild-type melanomas overall (37/1882)." (PMID 32483240, 2020). "Differentiated osteoblasts in turn can support melanoma cell proliferation and survival via the secretion of RANKL that elevates the levels of the transcription factor MITF, even in the presence of BRAF inhibitor." (PMID 31323160, 2020). "In general, the BRAF and NRAS status defined the nature of the proliferative apparatus, which has been well established as a major molecular biomarker of melanoma." (PMID 32411243, 2020). "In this study, we comprehensively studied the role and function of AURKB in melanoma, especially the interaction between AURKB and the BRAF/MEK/ERKs and PI3-K/AKT pathways." (PMID 32863956, 2020). "The combination of encorafenib (a BRAF inhibitor) and binimetinib (a MEK inhibitor) was recently approved by the FDA for the treatment of patients with advanced melanoma." (PMID 32260561, 2020). "Two pathways predicted the response to BRAF and MEK inhibitors in melanoma cell lines: the CREB and NFAT pathways." (PMID 32620799, 2020). "The BRAF inhibitors vemurafenib, dabrafenib and encorafenib are approved for use in the treatment of patients with BRAFV600-mutant advanced melanoma." (PMID 32645969, 2020). "However, inherent or acquired resistance of melanoma cells to BRAF inhibitors necessitates the discovery of new and improved anticancer agents, which work by suppressing other relevant molecular targets that play critical roles in the development and progression of melanoma." (PMID 32340351, 2020). "This resulted in preclinical tests of simultaneous BRAF and HSP90 inhibition and later a successful phase I clinical trial involving unresectable BRAF mutant melanoma." (PMID 32545208, 2020). "Anti-BRAF and anti-MEK therapies lead melanoma cells to a positive clonal selection, driving acquired mutation resistance." (PMID 33233603, 2020). "In this study, we identified AURKB as a critical target for drug-sensitive and - resistance melanoma treatment and found that HI-511 effectively suppressed development of vemurafenib-resistant melanoma by targeting both AURKB and BRAF V600E." (PMID 32863956, 2020). "Patients treated with BRAF inhibitors alone or in combination with MEK inhibitors have shown high objective response rates but have limited therapeutic duration and melanomas recur in almost every patient due to the development of drug resistance." (PMID 32231230, 2020). "Today, many virus vectors have demonstrated promising efficacy in combination with standard melanoma therapy, including immunotherapy, either in the form of MEK and BRAF inhibitors or in combination with chemotherapy (dacarbazine and cisplatin)." (PMID 32187995, 2020). "Even though such an expression pattern can be observed in cells unexposed to BRAF inhibitors, a low MITF/high AXL pattern would be increased as the melanoma progresses." (PMID 32605090, 2020).